MSI2 (musashi RNA binding protein 2)
Diseases named in the same sentence as MSI2 in open-access papers (continued):
Sharing a sentence is not in itself a finding about the gene and the disease.
myeloid leukemia (24 papers, 2014 to 2026). A clonal proliferation of myeloid cells and their precursors in the bone marrow, peripheral blood, and spleen. "In this study, we have explored the molecular mechanisms that underlie translational repression by MSI2 in myeloid leukemia cells." (PMID 35528200, 2022). "In the context of hematologic malignancies, MSI2 is required for the development and progression of myeloid leukemias." (PMID 41498402, 2026). "Upregulation of both Musashi homologues MSI1 and MSI2 has been reported in numerous neoplasms, including aggressive myeloid leukemia." (PMID 35528200, 2022). "MSI2 has been shown to be mainly expressed in hematopoietic stem cells, and it markedly regulates normal hematopoiesis and promote aggressive myeloid leukemia." (PMID 34212178, 2021). "Collectively, these data show that the Msi2-reporter model can be an effective tool to identify therapy-resistant cells in myeloid leukemia." (PMID 33243988, 2020). "To test if Msi2-reporter activity can effectively identify LSCs and therapy resistance in myeloid leukemia, we used a BCR-ABL/NUP98-HOXA9-driven model of bcCML21." (PMID 33243988, 2020). "Consistent with other reports, they observed that Msi2 in immature myeloid leukemia in which blast crisis had been reconstructed was induced." (PMID 31231484, 2019). "Previous studies show that MSI2 is overexpressed in various tumors, such as aggressive myeloid leukemia, hepatocellular and pulmonary cancers." (PMID 27092875, 2017). "In myeloid leukemia cells, MSI2 is highly expressed, and depletion results in decreased proliferation and increased apoptosis." (PMID 24935936, 2014). "Ultimately, MSI2 expression levels are directly correlated with poor prognosis in myeloid leukemia patients." (PMID 24935936, 2014). "As an important molecule in hematopoietic cells, the RNA binding protein Musashi‐2 (MSI2) is a heterogeneous ribonucleoprotein that was first discovered in myeloid leukemia and is considered an important marker for maintaining the stemness of hematopoietic stem cells." (PMID 39969091, 2025). "MSI2 plays a key role in hematopoietic stem cell activation, myeloid leukemia, and chronic lymphocytic leukemia (CLL) and its expression correlates with poor prognosis in multiple hematological malignancies, but its role in B-cell lymphoma is not currently known." (PMID 36167829, 2022). "Msi2 gene has been identified as a significant indicator for myeloid leukemia." (PMID 31231484, 2019). "Firstly, MSI2 is identified in stem and progenitor cells that regulates differentiation and to be a critical regulator of hematopoietic stem cell self-renewal in myeloid leukemia and myelodysplastic syndrome." (PMID 31888685, 2019). "Recently, the RNA-binding protein Musashi 2 (MSI2), which is a potent oncogene in myeloid leukemia and gastrointestinal malignancies, was found to enhance CSC properties, including self-renewal, drug resistance and tumorigenicity, by activating LIN28 in a mouse xenograft model of HCC14." (PMID 30237545, 2018). "But MSI2-Numb interaction was ubiquitously observed in myeloid leukemia." (PMID 27092875, 2017). "Msi2 and Notch signaling are upregulated in the course of human myeloid leukemia progression." (PMID 27441652, 2016). "Loss of MSI2 restores NUMB expression and impairs the blast crisis phase of myeloid leukemia." (PMID 24935936, 2014). "We then tested the effect of the pharmacological inhibition of MSI2 using Ro 08-2750 (Ro), a small molecule that inhibits MSI RNA-binding activity and has anti-proliferative activity in myeloid leukemia cells and chronic lymphocytic leukemia." (PMID 36167829, 2022). "The Hungarian sample had a 244.4 long overlapping homozygous region within the Musashi RNA binding protein 2 (MSI2), which is involved in stem cell proliferation, haematopoiesis and can promote aggressive myeloid leukaemia in humans." (PMID 30836959, 2019).
myeloid leukemia (continued). "Not only the overexpression of Msi2 is a weak marker in the progression of human CML, but it is also related to the rapid progression and poor prognosis in myeloid leukemia." (PMID 31231484, 2019). "Mounting evidence shows that MSI2 is an important proliferation/differentiation modulator in normal hematopoietic, embryonic stem cells (ESC) and myeloid leukemia." (PMID 27092875, 2017). "Moreover, we found previously that MSI2 binds and regulates c-MYC translation in myeloid leukemia cells." (PMID 36167829, 2022). "Ro treatment in mouse and human myeloid leukemia cells results in an increase in differentiation and apoptosis, inhibition of known MSI-targets, and a shared global gene expression signature similar to shRNA depletion of MSI2." (PMID 31217428, 2019). "It is also important to note that Ro inhibits both MSI1 and MSI2 and although MSI1 is expressed at low levels in myeloid leukemia it could still be blocking residual MSI1 activity." (PMID 31217428, 2019).
pancreatic cancer (22 papers, 2017 to 2026). "In pancreatic cancer, loss of MSI2 has been shown to lead to a defect in progression from PanIN to adenocarcinoma, exerting its impact through powerful oncogenes such as Met and epigenetic regulators such as BRD4 and HMGB2." (PMID 41498402, 2026). "The expression levels of NLK and MSI2 in pancreatic cancer tissues in nude mouse were verified by Western Blot." (PMID 39097735, 2024). "The mRNA levels of NLK showed the most significant changes in response to MSI2 knockdown and overexpression in pancreatic cancer cell lines, as observed in Capan-2 cells (MSI2-Ctrl VS MSI-Sg) and Panc-1 cells (Lv-Vector VS Lv-MSI2)." (PMID 39097735, 2024). "MSI2 also promotes EMT induced by EGF in pancreatic cancer through the ZEB1-ERK/MAPK signaling pathway." (PMID 39097735, 2024). "MSI2 also facilitates EMT in pancreatic cancer induced by EGF through the ZEB1-ERK/MAPK signaling pathway." (PMID 39097735, 2024). "In vitro and in vivo experiments were conducted to investigate the role and mechanism of MSI2 in promoting malignant behaviors of pancreatic cancer through regulation of NLK." (PMID 39097735, 2024). "Our findings elucidate the regulatory mechanisms of the MSI2-NLK axis in modulating aggressive behaviors of pancreatic cancer cells, which providing new evidence for therapeutic strategies in pancreatic cancer." (PMID 39097735, 2024). "This study aims to further explore the molecular mechanisms of MSI2-regulated downstream pathways in pancreatic cancer." (PMID 39097735, 2024). "For instance, MSI1 and MSI2 were found to be potentially “druggable” by antisense oligonucleotides in a human pancreatic cancer line and a pancreatic cancer mouse model." (PMID 39682684, 2024). "This study is the first to report the role of NLK in the progression of pancreatic cancer and confirms that MSI2 promotes pancreatic cancer development and affects prognosis by directly binding to NLK." (PMID 39097735, 2024). "Our previous research has shown that overexpression of MSI2 can promote the invasion and metastasis of pancreatic cancer cells by downregulating Numb." (PMID 39097735, 2024). "EGF‐induced EMT seems to require the function of the RNA‐binding protein Musashi2 (MSI2) by interaction with ZEB1 to facilitate ZEB1‐ERK/MAPK signaling in pancreatic cancer." (PMID 34459003, 2021). "In our previous study, we proved that MSI2 overexpression was positively associated with tumour size, UICC stage and poor prognosis of pancreatic cancer patients." (PMID 32779876, 2020). "In current study, ISYNA1 was downregulated in pancreatic cancer tissues and was negatively related to MSI2 expression, T stage, vascular permeation and poor prognosis of PC patients." (PMID 32779876, 2020). "In summary, MSI2 accelerates the development and progression of pancreatic cancer through a novel ISYNA1‐p21/ZEB‐1 pathway, which supplies a novel gene targets in the PC treatment." (PMID 32779876, 2020). "In vivo, MSI2 silencing inhibited pancreatic tumors in situ and liver metastasis, which was consistent with the studies in lung and esophageal squamous cell carcinoma." (PMID 31952541, 2020). "The loss of tumor suppressor APC resulted in the activation of MSI-2 in colorectal cancer, and reduced expression KLF4 (a transcriptional repressor of MSI-2) led to MSI-2 overexpression in pancreatic cancer." (PMID 29073938, 2017). "Overexpression of MSI2 has led to drug resistance in ovarian cancer cells, promotes invasion and metastasis in colorectal cancer, non-small cell lung cancer and pancreatic cancer." (PMID 29290973, 2017).
pancreatic cancer (continued). "MSI2 has emerged as a pivotal regulator of pancreatic cancer progression." (PMID 41049614, 2025). "It was demonstrated that MYC preferentially triggers transformation of the most immature MSI2+ pancreas cells into multi-lineage pre-cancer cells, which diverge to establish pancreatic cancer subtypes by activating distinct transcriptional programs and large-scale genomic changes." (PMID 41255572, 2025). "Moreover, single-cell transcriptomic profiling uncovers MSI2+ cells as multipotent precursors for diverse pancreatic cancer subtypes." (PMID 41049614, 2025). "Similarly, MSI2 and HIST1H1C have been associated with metastasis of pancreatic cancer, while TOP1 is associated with metastatic breast cancer." (PMID 41301029, 2025). "In our study, the expression of MSI2 is positively correlated with NLK in pancreatic cancer." (PMID 39097735, 2024). "Interestingly, in pancreatic cancer, a high proportion of circulating tumor cells (CTCs) expressed Msi2 (Msi2+), and were more tumorigenic than Msi2− CTCs, posing a greater risk for tumor dissemination." (PMID 37107676, 2023). "MSI2 overexpression is correlated with poor prognoses of liver and pancreatic cancer patients." (PMID 35288483, 2022). "Msi2 is proposed to be a marker of pancreatic cancer stem cells and a target gene of RORγt." (PMID 34752458, 2021). "Moreover, high expression of MSI2 with low ISYNA1 expression was found in serial pancreatic cancer sections and vice versa." (PMID 32779876, 2020). "Thus, the overexpression of MSI2 facilitates cell migration and cell invasion in pancreatic cancer by regulating ISYNA1‐ZEB‐1 pathway." (PMID 32779876, 2020). "In vivo, MSI2 silencing inhibited pancreatic tumor size in situ and distant liver metastases." (PMID 31952541, 2020). "MSI2 has recently been found to be over-expressed in many cancers, including hematologic malignancies, colorectal adenocarcinomas, lung, pancreatic cancers, and glioblastoma." (PMID 29290973, 2017). "We further verified the role of MSI2 in the EMT and PI3K-AKT-mTOR signaling pathway of pancreatic cancer cells through rescue experiments." (PMID 39097735, 2024). "Immunohistochemical results showed that MSI2 is primarily expressed in the cytoplasm, while NLK is expressed in both the cytoplasm and the nucleus of pancreatic cancer cells, and there is close correlation between MSI2 and NLK expression." (PMID 39097735, 2024). "To further verify the regulation of MSI2 and NLK on pancreatic cancer cells in vivo, we performed nude mouse transplantation tumor experiments." (PMID 39097735, 2024). "And in multivariate analysis, the expression of MSI2 and ISYNA1 were independent unfavourable prognostic indicators for pancreatic cancer." (PMID 32779876, 2020). "Building on our previous research, this study further confirms that MSI2 can affect EMT by regulating NLK, and both of them together promote the deterioration of the prognosis of pancreatic cancer patients, which also provides a potential target for EMT-targeted therapy in pancreatic cancer." (PMID 39097735, 2024). "Through in vivo and in vitro experiments, we revealed that MSI2 directly binds to the NLK mRNA to maintain its stability and promote the invasion and migration of pancreatic cancer cells, and NLK promotes pancreatic cancer progression through the EMT and PI3K/AKT/mTOR signaling pathway." (PMID 39097735, 2024).
pancreatic cancer (continued). "The regulation of PI3K/AKT/mTOR signaling by MSI2 and NLK in pancreatic cancer is still unclear." (PMID 39097735, 2024). "Additionally, evidence for crosstalk between MSI2 and p-ERK(P42/44) has been observed in pancreatic cancer and leukemic cells." (PMID 38041016, 2023). "Indeed, functional studies demonstrated a role of MSI2 in maintaining stemness properties, metastatic capacity, in vitro and in vivo tumorigenic ability and promoting drug resistance either in HCC or pancreatic tumors." (PMID 37107676, 2023).
acute myeloid leukemia (20 papers, 2012 to 2025). Acute myeloid leukemia (AML) is a group of neoplasms arising from precursor cells committed to the myeloid cell-line differentiation. "High expression of MSI2 mRNA is associated with decreased survival in acute myeloid leukaemia." (PMID 32828126, 2020). "Ro 08-2750 (Ro) is a small molecule that binds selectively to the MSI2 RNA-binding site, leading to MSI2 loss of function and affecting the survival of acute myeloid leukemia (AML) and chronic lymphocytic leukemia (CLL) cells." (PMID 36509891, 2023). "The same research group later, in a separate study, identified and characterized the small molecule Ro 08-2750 (Ro) as an inhibitor targeting the Musashi (MSI) family of RBPs, particularly MSI2, in the context of acute myeloid leukemia (AML)." (PMID 39456596, 2024). "Regarding MSI-targeting, another recent study identified a small molecule Ro 08-2750 that was effective against acute myeloid leukemia (AML) via suppression of highly expressed MSI2." (PMID 35158774, 2022). "Knocking down of MSI2 sensitizes cancer cells to treatment in ovarian cancer cells and in acute myeloid leukemia, MSI2 depletion stimulates an epithelial to mesenchymal phenotype." (PMID 29290973, 2017). "RNA-binding protein Musashi-2 (Msi2) is known to play a critical role in leukemogenesis and contributes to poor clinical prognosis in acute myeloid leukemia (AML)." (PMID 26308531, 2015). "Similarly, Msi2 is highly expressed in Acute Myeloid Leukemia (AML) cell lines, indicating a positive correlation with high-grade hematologic malignancies." (PMID 38411768, 2024). "The MSI2 RNA-binding protein has been demonstrated to have a role in acute myeloid leukaemia and stem cell function, but its role in MDS is unknown." (PMID 26898884, 2016). "A paradigmatic example is the balanced translocation involving UBE3C and MSI2, implicated in the pathogenesis of acute lymphoblastic leukemia (ALL) and aggressive acute myeloid leukemia (AML) subtypes, which can be precisely delineated by OGM." (PMID 41228238, 2025). "The previous studies have revealed that abnormal RNA-binding protein Musashi-2 (MSI2) expression is associated with cancer progression through post-transcriptional mechanisms, however mechanistic details of this regulation in acute myeloid leukemia (AML) still remain unclear." (PMID 37149661, 2023). "Musashi-2 protein (MSI2) is overexpressed in acute myeloid leukemia (AML) cell lines, and high expression of MSI2 promotes proliferation and inhibits apoptosis of AML cells." (PMID 34976013, 2021). "For example, in acute myeloid leukemia (AML), MSI2 expression has been shown to be an adverse prognostic marker that maintains the self-renewal program in AML by interacting with HOXA9, MYC, and IKZF2 mRNAs." (PMID 32448269, 2020). "Importantly, recent studies have shown Msi2 is overexpressed in chronic myelogenous leukemia (CML) and acute myeloid leukemia (AML)." (PMID 22496868, 2012).
chronic myeloid leukemia (18 papers, 2012 to 2025). "Recently, it was also elucidated that MSI2 regulates hematopoietic stem cells and is linked with acute and chronic myeloid leukemia." (PMID 28814279, 2017). "Previous work showed that Msi-2 overexpression and knockdown strategies influence proliferation and differentiation of HSCs and myeloid progenitors, through increased c-myc levels, associated with blastic crisis in chronic myeloid leukemia and poor outcome in AML." (PMID 28491035, 2017). "A role for dysregulated MSI2 expression in cancer was first reported in aggressive myeloid neoplasms such as chronic myelogenous leukemia (CML) in myeloid blast crisis and aggressive acute myeloid leukemia." (PMID 35528200, 2022). "Musashi2 (MSI2) was shown to bind to MSI binding sites in the 3′ untranslated region of BCAT1 in human chronic myeloid leukemia cell lines and positively regulate BCAT1 transcription." (PMID 36358687, 2022). "The Msi2 reporter also marked LSCs in chronic myeloid leukemia and in an NPM1-driven model of myeloproliferative disease." (PMID 33243988, 2020). "Recently, MSI2 dysregulation has been reported in various hematology and solid tumors, including acute and chronic myeloid leukemia (AML and CML), brain, lung, gastric, hepatocellular and bladder cancers." (PMID 31952541, 2020). "Specifically, we carry out a high throughput screen using Msi2-reporter blast crisis chronic myeloid leukemia (bcCML) and identify several adhesion molecules that are preferentially expressed in therapy resistant bcCML cells and play a key role in bcCML." (PMID 33243988, 2020). "Msi2 has been found to activate Notch signaling by binding to the mRNA of Numb and preventing its translation in a murine model of chronic myeloid leukemia (CML)." (PMID 26308531, 2015). "Most recently, a new posttranscriptional regulator of BCAT1 expression was identified in chronic myeloid leukemia (CML), the musashi RNA binding protein 2 (MSI2) [18▪▪]." (PMID 29211698, 2018). "Overexpression of others genes included in our signature, MSI2 (Musashi 2) and SOCS2 (Suppressor of cytokines signaling 2), predicted unfavorable outcome in AML and chronic myeloid leukemia (CML)." (PMID 22910040, 2012).